MIR3200 (microRNA 3200)
Synonyms: hsa-mir-3200; mir-3200
Gene: MicroRNA gene on chromosome 22 (30,731,557 to 30,731,641, forward strand). Ensembl gene ENSG00000264661.
Homologues: Orthologues: chimpanzee MIR3200 (100% identical).